VIM (vimentin)
Diseases named in the same sentence as VIM in open-access papers (continued):
Sharing a sentence is not in itself a finding about the gene and the disease.
bladder cancer (continued). "Secretion of vimentin by tumor endothelial cells can lead to immunosuppression, and vaccination to produce anti-vimentin antibodies shows efficacy in prolonging survival in dogs with bladder cancer." (PMID 39910535, 2025). "Furthermore, we detected the protein levels of E-cadherin, N-cadherin, and Vimentin in bladder carcinoma cell lines (UMUC3 and T24) after transfection with OE-circLRIG1 plasmids by utilizing Western blot analysis." (PMID 38454507, 2024). "Based on our study, TWIST1 and Vimentin promoter methylation could distinguish bladder cancer patients from healthy/benign subjects with 78% sensitivity and 83% specificity in urine samples." (PMID 38575639, 2024). "Finally, we used Western blot analysis to detect the protein levels of E-cadherin, N-cadherin and Vimentin in bladder carcinoma cell lines (UMUC3 and T24)." (PMID 38454507, 2024). "Additionally, Western blot analysis revealed that LRIG1 overexpression increased the protein level of E-cadherin but decreased the protein level of N-cadherin and Vimentin in bladder carcinoma cells." (PMID 38454507, 2024). "Results showed that circLRIG1 overexpression could elevate the protein level of E-cadherin while reducing the protein levels of N-cadherin and Vimentin in bladder carcinoma cells." (PMID 38454507, 2024). "Moreover, we validated the interactions between FAM171B and vimentin/HNRNPU in MB49 bladder cancer cells from mice." (PMID 37915048, 2023). "To investigate whether FAM171B enhances the invasion and migration of bladder cancer cells through vimentin, we conducted wound healing and transwell invasion assays in cells treated with Vimentin-IN-1." (PMID 37915048, 2023). "Targeting FAM171B to reduce vimentin levels could offer a promising strategy for preventing metastasis in patients with advanced bladder cancer." (PMID 37915048, 2023). "Previous results demonstrated the interaction between FAM171B and vimentin in bladder cancer cells." (PMID 37915048, 2023). "We generated organoids from two upper tract urothelial carcinomas and from one bladder cancer sample, and confirmed the expression of cytokeratins as urothelial antigens, vimentin as a mesenchymal marker, and fibroblast growth factor receptor 3 by immunohistochemistry." (PMID 35682984, 2022). "Importantly, vimentin has been found to be an important biomarker for the process of epithelium–mesenchyme transition in bladder cancer." (PMID 36131933, 2022). "Transwell assays revealed that HMGN5 or Hsp27 overexpression alone could significantly promote bladder cancer cell invasion and decrease E-cadherin expression and increase Vimentin expression." (PMID 32315283, 2020). "al. showed three novel gene loci, i.e., GDF15, TMEFF2, and VIM, whose DNA methylation could be suitable for detecting bladder cancers in urine samples." (PMID 32046186, 2020). "Maspin acts as an HDAC1 inhibitor, which may modulate the p21, cyclin D1, MMP9, and vimentin expressions in bladder carcinoma cells." (PMID 31861435, 2019). "Few studies about the roles of Vimentin in bladder cancer had been published." (PMID 28166762, 2017). "The role of Vimentin in predicting progression of bladder cancer is obscure." (PMID 28166762, 2017). "On the other hand, we also observed that miR-199a-5p could directly target the 3′UTR of CCR7 and regulate the expression of MMP-9 and EMT-related proteins like vimentin and E-cadherin, eventually suppress the progression of bladder cancer." (PMID 27814720, 2016). "Interestingly, we demonstrated that miR-186 mimics and NSBP1 siRNA inhibited EMT and were associated with reduced expression of E-cadherin and elevated expression of N-cadherin and vimentin in bladder cancer." (PMID 26290438, 2015). "Therefore, it can be concluded that cytokeratin and vimentin will be helpful markers in the early diagnosis of Transitional Cell Carcinoma/bladder carcinoma." (PMID 26640315, 2015).
bladder cancer (continued). "Different expression pattern of vimentin was also noticed in bladder cancer and normal urothelia." (PMID 26640315, 2015). "In bladder cancer cells ZEB1 regulates vimentin, MMP2 and cytokeratins." (PMID 26098771, 2015). "Techniques for detecting bladder cancer based on urine DNA or RNA, such as the detection of mutations and methylation of telomerase reverse transcriptase (TERT), Fibroblast growth factor receptor 3 (FGFR3), Vimentin (VIM), and One Cut Homeobox 2 (ONECUT2) genes, have become the focus of research." (PMID 41281744, 2025). "Therefore, Dectin-1 may also modulate T-cell function through vimentin activation in bladder cancer, but further experiments are required to verify this hypothesis." (PMID 36131933, 2022). "Furthermore, mesenchymal markers, Twist and Vimentin, are related to the stage and grade of bladder cancer and could strongly affect the progression and metastasis of bladder cancer." (PMID 32315283, 2020). "We show that VFL induces cell death in bladder cancer cells and activates epithelial differentiation of the remaining living cells, leading to an increase of E-cadherin-dependent cell-cell adhesion and a reduction of mesenchymal markers, such as N-cadherin or vimentin." (PMID 25012153, 2014). "In human bladder cancer cell lines, we observed a direct correlation between E-cadherin and p63 expression, and an inverse correlation between these markers and Zeb-1, Zeb-2, and vimentin, indicating they cluster into unique “epithelial” and “mesenchymal” subsets." (PMID 22253920, 2012). "SLC12A8 is highly correlated with the oncogenesis and progression of bladder cancer and promotes the expression of EMT protein markers, including β-catenin, vimentin, snail, and slug, through the JAK/STAT pathway." (PMID 40299526, 2025). "The results showed that SBSPON overexpression induced an epithelial phenotype by reducing mesenchymal markers (Vimentin, N-cadherin and Snail) while increasing the epithelial marker E-cadherin, suggesting that SBSPON inhibits EMT in bladder cancer cells." (PMID 40765821, 2025). "Our previous study observed that ISO downregulated vimentin, one of the EMT markers, suppressing invasion in human bladder cancer cells." (PMID 40362444, 2025). "In this study, among the 77 bladder cancer patients, the TWIST1/Vimentin positivity was significantly high, reaching 77.9%, whereas, in individuals with other urological malignancies, the positivity rate was only 18.5%." (PMID 38575639, 2024). "In bladder cancer, α-SMA- and vimentin-expressing CAFs have been shown to be most prominent in invasive tumors." (PMID 38607066, 2024). "Immunoprecipitation using anti-DYKDDDDK and anti-HA beads confirmed the interactions of FAM171B with vimentin and HNRNPU in MB49 mouse bladder cancer cells." (PMID 37915048, 2023). "The upregulation of cytokeratin 18 and cytokeratin 19 (epithelial markers) and the downregulation of vimentin, N-cadherin, MMP2, and ZEB1 (mesenchymal markers) were observed in the bone metastatic T24-B bladder cancer cells." (PMID 37627900, 2023). "Next, we inhibited protein synthesis in bladder cancer cells using cycloheximide (CHX), and subsequently measured the level of remaining vimentin protein by western blotting." (PMID 37915048, 2023). "Our experimental findings demonstrated the impact of FAM171B on both vimentin and the CCL2-CCR2 axis, which significantly influences the progression of bladder cancer." (PMID 37915048, 2023). "We revealed a new mechanism whereby TGF-β1 dominated stromal fibroblast-mediated EMT of bladder cancer cells via the FAP/VCAN axis and identified potential biomarkers (FAP, VCAN, N-cadherin, and Vimentin) of bladder cancer." (PMID 37461061, 2023). "On the other hand, both targeting vimentin and the CCL2-CCR2 axis show promise as therapeutic strategies for bladder cancer." (PMID 37915048, 2023).
bladder cancer (continued). "In urine samples, the methylation status of a urinary biomarker panel (HOXA9, ONECUT2, PCDH17, PENK, TWIST1, VIM, and ZNF154) showed great prediction accuracy in predicting bladder cancer in patients with hematuria." (PMID 37627900, 2023). "Our study uncovered a novel mechanism for regulating vimentin at the protein level in bladder cancer and partially explains the relationship of FAM171B with poor prognosis in bladder cancer." (PMID 37915048, 2023). "Collectively, these findings highlight vimentin and HNRNPU as the primary interacting proteins of FAM171B in bladder cancer cells." (PMID 37915048, 2023). "Vimentin (VIM), identified as a promising bladder cancer methylation biomarker in our previous study, was included in subsequent analyses." (PMID 36115961, 2022). "COL6A3 silencing suppresses the expression of MMP-2, MMP-9, and vimentin, then participates in the process of inhibiting EMT of bladder cancer cells." (PMID 35774273, 2022). "These alterations in Vimentin, Twist, N‐cadherin, and E‐cadherin levels further proved and explained the promotive roles of CERCAM overexpression in the ability of bladder carcinoma cells to proliferate and to invade." (PMID 34105305, 2021). "DPYSL2 overexpression also significantly attenuated E-cadherin protein expression, while enhancing Vimentin and ZEB1 protein expression in bladder cancer cells." (PMID 34295887, 2021). "For instance, miR-22 suppresses epithelial–mesenchymal transition in bladder cancer by inhibiting Snail and MAPK1/Slug/vimentin feedback loop." (PMID 34238129, 2021). "DPYSL2 overexpression significantly attenuated E-cadherin protein expression while enhancing Vimentin and ZEB1 protein expression in bladder cancer cells." (PMID 34295887, 2021). "In another study, the correlation between the methylation levels of EOMES, HOXA9, POU4F2, TWIST1, VIM, and ZNF154 in urine specimens and bladder cancer recurrence surveillance was discovered by real-time PCR." (PMID 33388091, 2021). "First, we found that exosomes secreted by CAFs reduced the apoptosis and promoted the metastasis and chemoresistance of bladder cancer cells by enhancing EMT, indicated by higher levels of N-cadherin and vimentin and lower levels of E-cadherin expression." (PMID 33423167, 2021). "Moreover, in bladder cancer, nucleolar and spindle associated protein 1 (NUSAP1) was upregulated, and its expression was closely related to the poor prognosis of patients, which was also demonstrated to regulate EMT via the TGF-β signaling pathway, as well as p-Smad2/3 and vimentin expression." (PMID 32456355, 2020). "T24-Exos or J82-Exos also induced the expression of the EMT-transcription factors Slug, Snail, Twist and Zeb2, which ultimately suppressed E-cadherin expression but promoted N-cadherin, vimentin, MMP2 and MMP9 expression in bladder cancer cells." (PMID 32517366, 2020). "We showed that the exposition of bladder cancer cells to the CAF conditioned medium (CM iCAF) significantly induced the expression of N-cadherin, vimentin, SNAIL1, TWIST1 and ZEB1 while repressing E-cadherin and phospho-ß-catenin expression." (PMID 30744595, 2019). "Here, we established a combination methylation assay of HOXA9, ONECUT2, PCDH17, PENK, TWIST1, VIM and ZNF154, which had displayed great prediction accuracy of bladder cancer in patients with hematuria by using urine samples." (PMID 31777606, 2019). "It was demonstrated that loss of miRNA-141 and miRNA-200b expression increases the invasion and migration capacities of bladder cancer cell lines and up regulates MMP-2, MMP-9, vimentin, N-cadherin while down regulates E-cadherin expression." (PMID 30544619, 2018). "Down-regulation of N-cadherin, vimentin, fibronectin, Zeb1, Twist, and Snail and up-regulation of E-cadherin were observed in CLCA4 overexpressed bladder cancer cells." (PMID 29190973, 2017).
bladder cancer (continued). "The investigated bladder cancer cell lines turned out to display quite different EMT patterns as indicated by the abundance of E-cadherin or N-cadherin and vimentin." (PMID 24325461, 2013). "Correlation analysis in bladder cancer samples from TCGA BLCA demonstrated a positive correlation between mRNA levels of IGF2BP3 and SNAI1 (Snail), SNAI2 (Slug), CDH2 (N-cadherin), VIM (vimentin), and MMP9, further supporting the association between IGF2BP3 and EMT-related markers." (PMID 38504159, 2024). "In addition, a 6-gene panel (HOXA9, EOMES, POU4F2, TWIST1, VIM, and ZNF154) was highly hypermethylated in the urine of bladder cancer patients as compared to healthy individuals." (PMID 37627900, 2023). "Furthermore, the results of Western blot illustrated that the expression of N-cadherin, Vimentin, and MMP9 was decreased in bladder cancer cells after over-expression of LINC00478 in T24 cells while being elevated following LINC00478 silencing in 5637 cells." (PMID 35504875, 2022). "Furthermore, the expression of vimentin was found to be positively correlated with indoleamine 2,3-dioxygenase 1 (IDO-1), which exerts crucial regulatory functions on T-cell functions in bladder cancer." (PMID 36131933, 2022). "In conclusions, a urinary combined methylation assay of HOXA9, ONECUT2, PCDH17, PENK, TWIST1, VIM and ZNF154 displayed accurate prediction of bladder cancer in hematuria patients, which provided the guidance for the patients at early stage tumor and during the follow-up after operation." (PMID 31777606, 2019). "In bladder cancer, miR-138 binds to the 3′TUR sequence of ZEB2 (zinc finger E-box binding homeobox 2), regulates the expression and phosphorylation of vimentin and e-cadherin, reverses the EMT process, and enables cancer cells to obtain epithelial characteristics." (PMID 31885571, 2019). "Moreover, in bladder carcinoma cells, maspin modulated HDAC1 target genes, including cyclin D1, p21, MMP9, and vimentin." (PMID 31861435, 2019). "Our results are consistent with this hypothesis, and we found that knockdown of lncRNA-UCA1 in hypoxic exosomes increased E-cadherin expression, while decreasing the expression levels of vimentin and MMP9 in bladder cancer cells or xenograft tumor tissues." (PMID 28841829, 2017). "An important study reported that expression of vimentin was observed in 43% of bladder cancers, whereas it was not expressed or found negative in all normal urothelia." (PMID 26640315, 2015). "One study reported that gigantol, a bibenzyl compound, inhibited the metastasis in bladder cancer cells through Wnt/β-catenin signaling, and another study showed that MiR-22 suppressed EMT progression through Snail and mitogen-activated protein kinase 1/Slug/vimentin." (PMID 33806566, 2021).
pulmonary fibrosis (96 papers, 2013 to 2026). Chronic progressive interstitial lung disorder characterized by the replacement of the lung tissue by connective tissue, leading to progressive dyspnea, respiratory failure, or right heart failure. "In our current investigation utilizing a vimentin-induced sarcoidosis model, we have successfully identified an enrichment of gene sets associated with lung fibrosis and tissue remodeling in the lung transcriptome following the vimentin challenge." (PMID 41476976, 2025). "In the lungs of LmnaG609G/G609G mice, an increased vimentin signal was observed near the pulmonary bronchioles, associated with tissue remodeling and lung fibrosis, and indicates functional loss of the pulmonary functional unit responsible for gas exchange." (PMID 39273272, 2024). "Vimentin has been previously linked to scarring phenotypes in corneal injury, and in bleomycin-induced lung fibrosis." (PMID 36297560, 2022). "Different types of amphibole asbestos were observed to induce antinuclear antibodies (ANA) including anti-SS-A/Ro and anti-dsDNA as well as autoantibodies against vimentin and fibroblasts, which were associated with lung fibrosis, in C56BL/6 mice." (PMID 34996462, 2022). "For example, siRNA against osteopontin (OPN) significantly inhibited EMT in bleomycin (BLM)-induced murine pulmonary fibrosis, as evidenced by increased E-cadherin, decreased vimentin, and reduced fibrotic remodeling." (PMID 40988754, 2025). "Three studies evaluated biomarkers for lung fibrosis (vimentin,α-SMA, surfactant protein-C, MCP-1, and Krebs von den lungen-6& KC) resulting from inflammation, and three studies evaluated biomarkers relatedto oxidative stress (ROS, SOD, GSH-PX, and CAT)." (PMID 39692326, 2024). "A significant decrease in E-cadherin and an increase in N-cadherin, α-smooth muscle actin (α-SMA), and vimentin were observed in BLM-induced pulmonary fibrosis group, confirming the activation of the EMT program." (PMID 39122680, 2024). "Studies using Vim−/− mouse models indicate that vimentin is essential for the development of pulmonary fibrosis, as its absence can alleviate the degree of fibrosis in mice." (PMID 39512901, 2024). "In this report, we used collagen-I, collagen-III, α-SMA, vimentin, and snail as biochemical indicators to evaluate the degree of pulmonary fibrosis." (PMID 38895626, 2024). "During EMT, the expression of mesenchymal markers such as α‐SMA, fibroblast‐specific protein‐1 (FSP1), vimentin and desmin increases, indicating increased pulmonary fibrosis." (PMID 38774993, 2024). "Both N-cadherin and vimentin contribute to the pathogenesis of pulmonary fibrosis by promoting fibroblast activation, migration, and tissue remodeling." (PMID 38276616, 2024). "PD-L1 can induce EMT in AECs to promote lung fibrosis by directly binding to vimentin and inhibiting vimentin ubiquitination." (PMID 38263193, 2024). "Further experiments are needed to understand the difference between the PAD enzymes in relation to citrullination of vimentin and development of lung fibrosis." (PMID 38155185, 2023). "Citrullinated vimentin was sufficient to promote fibroblast activation in vitro and elicit profibrotic cytokine production and lung fibrosis in vivo, indicating that the PAD enzymes are a promising target to attenuate lung fibrosis." (PMID 38155185, 2023). "In a recent in vivo study citrullinated vimentin was also shown to mediate development and progression of lung fibrosis through TLR4-dependent NF-κB activation." (PMID 38155185, 2023). "Our results are consistent with another study, as BLM-activated EMT has been found to increase the protein expression of α-SMA and Vimentin and decrease E-cadherin and ZO-1 in pulmonary fibrosis." (PMID 37427320, 2023). "We verified that HDAC3 deficiency in AT2 cells alleviated BLM-induced pulmonary fibrosis in mice and TGF-β1-induced EMT in vitro, as evidenced by increased E-cadherin expression and decreased N-cadherin and vimentin expression." (PMID 37951958, 2023).